CCL18 (C-C motif chemokine ligand 18)
Diseases named in the same sentence as CCL18 in open-access papers (continued):
Sharing a sentence is not in itself a finding about the gene and the disease.
cancer (continued). "Taken together, our findings highlight the relevance of CCL18 and EGF in cancer biology and underscore their potential as biomarkers, where their expression changes may have diagnostic and therapeutic implications." (PMID 40692603, 2025). "Additionally, through producing CCL18, which binds to PITPNM3 on the cancer cell membrane, TAMs in breast cancer increase the invasiveness of cancer cells." (PMID 36825088, 2023). "Notably, the importance of CCL18 in neoplastic processes mainly includes a signal transduction from PITPNM3 (one of CCL18 receptors) in CCL18-dependent migration, invasion, and epithelial- EMT cancer cells." (PMID 38347955, 2023). "Some studies indicated that macrophages exposed to hypoxia/lactate may secrete IL-6, TNF-α, CCL5 and CCL18, which favor glycolysis and boost synthesis of pro-glycogenic factors in TME in some cancers." (PMID 36362348, 2022). "No less a significant receptor for CCL18 in cancer processes is CC motif chemokine receptor 8 (CCR8)." (PMID 35955670, 2022). "To further determine whether CCL18 and BCL2A1 could be used as predictive biomarkers for cancer immunotherapy, such as cisplatin IC50, we investigated their relationship with hallmarks of genomic instability (biomarkers for immunotherapy)." (PMID 35265629, 2021). "Additionally, cancer-cell-derived CCL2, CCL18, CCL17 and CXCL4 work in concert to polarize macrophages towards M2-like phenotypes." (PMID 34638388, 2021). "Besides, both CCL18 and BCL2A1 were significantly related to the occurrence and development of cancer." (PMID 35265629, 2021). "In line with the idea that CCL18 is a stimulator of PKCδ signaling, our data demonstrated that blocking CCL18 signaling suppressed the expression of the PKCδ downstream factors STAT3 or NF-κB as well as various cancer-related factors." (PMID 31126309, 2019). "CCL18 from TAMs induces cancer cell EMT and increases cancer metastasis." (PMID 28567162, 2017). "Our results demonstrated that in the presence of ionizing radiation either RKO or SW1463 cancer cells increased mRNA expression levels of the macrophage pro-inflammatory markers TNF, IL6, CCL2 and CCR7 as well as of the anti-inflammatory marker CCL18." (PMID 27513864, 2016). "Taken together, these data provide evidence that elevated CCL18 in OSCC is attributed to cancer epithelial cells as opposed to TAMs." (PMID 26919103, 2016). "Interestingly, when macrophages were cocultured with radioresistant cells, both proinflammatory (CCR7, CD80) and anti-inflammatory markers (IL-10 and CCL18) were overexpressed, with no changes in cancer cell migration and invasion." (PMID 37347290, 2023). "The significant KEGG pathways are chemokine signaling pathway (CCL5, CCL18, CCL19, CCL21, CXCL12, CXCL14, CXCL13), ​​NF-kappa B signaling pathway (CCL19, CCL21, CXCL12), intestinal immune network for IgA production (TNFRSF17, CXCL12), pathways in cancer (IGF1, CXCL12)." (PMID 35486660, 2022). "In addition, transcription of the chemokines CCL18 and CCL17 was decreased in the cancer group." (PMID 28350008, 2017). "However, there are no available data on the anti-cancer properties of CCL18." (PMID 33114763, 2020). "CCL18, CCL22, CCL23, and CXCL12 consistently showed a negative correlation across most cancer types, while other anti-inflammatory chemokine genes displayed a more complex, context-dependent relationship, with both positive and negative correlations depending on the specific malignancy." (PMID 40806276, 2025). "Additionally, our analysis of chemokines revealed a strong positive correlation between EXO1 expression and CCL7, CCL13, and CCL18 in BRCA, OV, THCA, and UCEC, while a negative correlation was observed with CCL14 and CCL16 in most female-related cancers." (PMID 40433389, 2025).
cancer (continued). "Subsequent M2-type TAMs secrete large amounts of several C-C motif chemokine ligand 18 (CCL18) and activate vascular cellular adhesion molecule-1 (VCAM-1) in cancer cells via noncanonical nuclear factor-κB (NF-κB) signaling to enhance the Warburg effect, which forms a positive feedback loop." (PMID 36578477, 2022).
infection (12 papers, 2015 to 2025). The state of being infected such as from the introduction of a foreign agent such as serum, vaccine, antigenic substance or organism. "In the ELISA quantification for CCL18, significant differences were identified in the comparisons between the infected and control at 48 and 96 h after infection." (PMID 38743668, 2024). "It was observed a decrease in CCL18 levels in the infected cells compared to the control after 48 and 96 h of infection." (PMID 38743668, 2024). "The E. multilocularis antigen (EmAg) inducible cellular productions of MCP1(CCL13), TARC(CCL17) and PARC(CCL18) were lowest in patients with cured AE and infection-free controls, while the EmAg inducible cellular production of IFN-γ increased after cure." (PMID 35108275, 2022). "In contrast, C-C motif chemokine ligand 18 (CCL18) was increased over the time course of infection by morphine, particularly in the chronic virus-suppressed time points." (PMID 36466814, 2022). "CCL3 and CCL4 are kept at the low levels until induction by inflammation or infection, but, in addition to being inducible by inflammatory and disease conditions, CCL18 is constitutively expressed at high levels in certain tissues." (PMID 25636406, 2015). "RB50ΔbtrS induced macrophages to produce significantly higher levels of CCL18 and IL-6 than did wild-type bacteria, suggesting the mutant might increase recruitment of B cells to the site of infection." (PMID 31889098, 2019). "The CC chemokines TARC(CCL17), PARC(CCL18) and LARC(CCL20) were measured in serum samples of AE patients and infection-free controls." (PMID 35108275, 2022). "Owing to the expression of chemokine receptors such as chemokine ligand 1 (CCL1), CCL18, and intercellular adhesion molecule-1 (ICAM-1) on M2-Exos, they can exhibit high recruitment of infection sites, thereby effectively solving the problem of poor targeting of existing Exos." (PMID 40177029, 2025). "CCL18, also known as pulmonary and activation regulated chemokine (PARC) among other names (e.g., MIP-4, DC-CK1, and AMAC-1), is a primate-specific CC chemokine expressed by macrophages, monocytes, and dendritic cells upon infection or inflammation to attract T cells." (PMID 25636406, 2015).
immune dysfunction (4 papers, 2019 to 2024). "Studies have demonstrated the crucial role of CCL18 in the progression of fibrotic immune diseases and tumors." (PMID 38511143, 2024). "Notably, CCL18 and IFNA4 emerged as prospective peripheral blood markers capable of identifying PTE‐induced immune disorders." (PMID 37700485, 2023).
adenocarcinoma (3 papers, 2012 to 2017). A common cancer characterized by the presence of malignant glandular cells. "We investigated the effect of CCL18 on A549, an adenocarcinoma cell line of the lung, on EMT and other cell functions like proliferation, chemotaxis, invasion, chemoresistance and proliferation." (PMID 23349697, 2013). "In conclusion, in patients suffering from adenocarcinoma increased serum CCL18 levels predict a diminished survival time." (PMID 22848587, 2012). "The heterogeneity of our study group also limits conclusions on the prognostic value of CCL18 for treatment response as only for adenocarcinoma a correlation between CCL18 and OS could be demonstrated." (PMID 28957436, 2017). "We, therefore, hypothesized that CCL18 is an inducer of EMT in human adenocarcinoma cells of the lung and enhances the metastatic potential." (PMID 23349697, 2013). "We could demonstrate that CCL18 is highly elevated in patients with NSCLC and correlates with T-stage and mean survival time in the adenocarcinoma subgroup." (PMID 23349697, 2013).
inflammation (2 papers, 2020 to 2024). Aberrant reaction of the microcirculation characterized by movement of fluid and leukocytes from the blood into extravascular tissues. "Plaques from CCL18-treated mice had decreased macrophage content, compatible with a more advanced plaque phenotype and tended to have increased collagen content, which is in line with CCL18’s reported pro-fibrotic activity in lung inflammation." (PMID 38807599, 2024). "Our findings indicate that CCL-18 and IL-23 participate in the inflammatory process of COPD and are correlated with irreversible airway inflammation and airflow restriction, so they may be used as inflammatory markers for disease evaluation and efficacy evaluation of COPD." (PMID 33082377, 2020).
bacterial infection (1 paper, 2016). "With regard to CCL18 and bacterial infection, CCL18 was induced in peripheral blood mononuclear cells by staphylococcal enterotoxins and in alveolar macrophages by lipopolysaccharide and tuberculous infection." (PMID 27293304, 2016).
colon polyps (1 paper, 2022). "The colon polyps demonstrated decreased expressions in CCL5, CCL18, CCL19, CCL21, CXCL12, CXCL14 and CXCL13 genes in this research." (PMID 35486660, 2022).
kidney disease (1 paper, 2021). "Serum CCL18 levels also correlated with kidney disease activity, being lower in patients with immunosuppressive rescue therapy and higher in relapsing kidney disease." (PMID 34307414, 2021). "Despite these comprehensive studies, there are no published data on CCL18 in other human kidney diseases." (PMID 34307414, 2021).
CCL18 also shares sentences with these, for which no sentence is quoted: gallbladder carcinoma (4 papers); pterygium (3); scleroderma (3); alopecia areata (2); benign ovarian tumors (2); gastric adenocarcinoma (2); gastric tumor (2); idiopathic interstitial pneumonia (2); infectious disease (2); ovarian serous cystadenocarcinoma (2); pancreatic adenocarcinoma (2); renal cell carcinoma (2); thyroid cancer (2); type 2 diabetes mellitus (2); acid sphingomyelinase deficiency (1); Allergy (1); anaemia (1); ANCA-associated vasculitis (1); Anxiety (1); aortic valve disease (1); arteriosclerosis (1); benign tumors (1); beta thalassemia (1); Brain atrophy (1); breast invasive ductal carcinoma (1); breast phyllodes tumor (1); burning mouth syndrome (1); cardiac hypertrophy (1); cardiovascular disease (1); cervical squamous cell carcinoma (1).
A further 52 diseases each share a sentence with CCL18 in 1 paper.